AR (androgen receptor)
Diseases named in the same sentence as AR in open-access papers (continued):
Sharing a sentence is not in itself a finding about the gene and the disease.
prostate carcinoma (continued). "The role of AR pathway in the osteoblastic progression of prostate cancer is poorly understood because available models of mixed and pure osteoblastic lesions (C4-2B, PCa2B, VCaP) are mainly androgen responsive like." (PMID 24069383, 2013). "Although activation of the AR by androgens is the most direct means of promoting prostatic growth, there are several surrogate pathways in prostate cancer." (PMID 24082997, 2013). "In the case of prostate cancer, the androgen receptor was shown to rapidly induce long-range interactions both in cis and in trans following ligand binding." (PMID 24019942, 2013). "Two signaling transduction pathways, namely PI3K/AKT and JAK/STAT3 pathways, have been shown to activate AR in prostate cancer cells." (PMID 23620780, 2013). "Both AR and c-Myc are critical survival pathways in prostate cancer, and expression levels of both AR and c-Myc are commonly increased in human CRPC tumors progressing despite ADT." (PMID 23704919, 2013). "The detection and AR regulation of Sox2 in castration-resistant CWR-R1 cells suggested that Sox2 expression increases in response to host castration or AR inhibition and thus promotes castration-resistant prostate cancer cell growth." (PMID 23326489, 2013). "A systematic analysis based on a gain-of-function screening of 1129 miRNAs by Ostling and colleagues identified 71 unique miRNAs that influenced the level of AR in human prostate cancer cells." (PMID 23896594, 2013). "Androgen, by activating androgen receptor (AR), plays an important role in both the development and progression of prostate cancer." (PMID 23437213, 2013). "In the AR-positive LNCaP prostate cancer cell line, which has lost one copy of the KLF5 genome, KLF5 appears to be a direct target and functional co-factor of AR in transcriptional regulation of AR target genes." (PMID 23755247, 2013). "In recurrent prostate cancer, AR amplification was common, with the reported frequency varying between 20% and 60%." (PMID 24098661, 2013). "In prostate cancer, for example, such genetic drivers include loss of NKX3.1 and PTEN, amplification of Myc and the androgen receptor (AR), Sox9, and fusions of ETS family transcription factors to androgen-inducible promoters." (PMID 23902736, 2013). "Reports from various groups have demonstrated that CXCL8 signaling activates multiple transcription factors such as NFκB, AP-1, HIF-1 and STAT3, and in prostate cancer cells, this signaling has been shown to induce activation of the androgen receptor (AR)." (PMID 24276377, 2013). "The levels of Vav3, a Rho GTPase guanine nucleotide exchange factor (GEF), are elevated in human prostate cancer specimens, and they increase during the progression of prostate cancer to androgen independence by enhancement of AR transcriptional activity." (PMID 23566222, 2013). "Our approach was to look downstream of AR, to an AR-regulated gene that is essential for the viability of cancer cells and progression of prostate cancer." (PMID 23724033, 2013). "Manipulating androgen/AR signaling can be a potential therapy for AR-positive advanced prostate cancers." (PMID 24349321, 2013). "Like the development of normal prostate, the growth and progression of prostate cancer are also dependent on androgens and AR." (PMID 23724033, 2013). "Another important mechanism of gene regulation in prostate biology and prostate cancer progression is the activation of the androgen receptor signaling pathway." (PMID 23409773, 2013). "For example, in prostate cancer, one of the most interesting regions is the AR-locus on chromosome Xq12, which is amplified in approximately 33% of patients with CRPC." (PMID 23561577, 2013). "In conclusion, targeting advanced prostate cancer largely involves inhibitors towards androgen synthesis and androgen receptor transactivation." (PMID 24163230, 2013).
prostate carcinoma (continued). "Sexual hormone receptors, such as AR and estrogen receptor, have been suggested to become therapeutic targets in sexual organ cancers, including prostate cancer and breast cancer." (PMID 23620780, 2013). "Androgens signaling through the AR play an essential role in normal prostate development and contribute to the progression of prostate cancer." (PMID 23405127, 2013). "Since sGCα1 is expressed in both hormone-dependent and -independent AR-positive cells, our expectation was that Peptide A-8R should be cytotoxic to both types of prostate cancer cells." (PMID 23724033, 2013). "It has been recently demonstrated that transgelin prevents the binding of the androgen receptor co-activator to the androgen receptor resulting in the inhibition of androgen-stimulated cell growth in prostate cancer cells." (PMID 23717685, 2013). "Further studies revealing detailed interactions between important survival factors and androgen receptor can make another basis in reinforcing therapeutic armaments combating fatal advanced prostate cancer." (PMID 23853530, 2013). "Androgens act through binding and transactivating the androgen receptor (AR), which regulates gene expression by interacting with different co-regulators during prostate cancer progression." (PMID 23743823, 2013). "The important regulatory role of androgens on the TMPRSS2:ETS fusion via interaction with the androgen receptor (AR) enables a new promise for a potential role of the gene fusions in predicting the emergence of castration resistant prostate cancer (CRPC)." (PMID 24018887, 2013). "A feasible and clinically relevant method is to pursue the identification of small molecules that can activate UPS-mediated degradation of proteins such as androgen receptor (AR) in prostate cancer (PC)." (PMID 23424652, 2013). "Cyp40 and FKBP1 are elevated in prostate cancer compared to normal cells, positively regulate androgen dependent prostate cancer growth, and increase AR-dependent transcription." (PMID 24278769, 2013). "In the TRAMP transgenic mouse model of prostate cancer, treatment with BA (10 mg/kg) inhibited primary tumors, increased apoptosis, decreased angiogenesis and proliferation, and lowered androgen receptor and cyclin D1 protein." (PMID 23424652, 2013). "We, therefore, sought to assess the effects of VK2 treatment on AR expression in androgen-dependent prostate cancer cells." (PMID 24062781, 2013). "AR knockdown strategies have been used to demonstrate that AR is required for proliferation of prostate cancer cells." (PMID 23437213, 2013). "Although AR plays an essential role in the carcinogenesis of prostate cancer, only a small minority of untreated prostate cancers harbor copy number alteration of AR gene." (PMID 23896594, 2013). "We sought the miRNA that are controlled by AR and involved in the negative regulation of prostate cancer progression." (PMID 24391862, 2013). "Most prostate cancers are initially androgen-dependent (AD) and are generally treated with a combination of radiotherapy, chemical castration, androgen-receptor (AR) antagonists (hydroxyflutamide, bicalutamide), or inhibitors of steroidogenesis (abiraterone)." (PMID 23940835, 2013). "NF-kB and STAT-3 (phosphorylated form of STAT-3) transcription factors and Androgen Receptor (AR) play a critical role in cell proliferation, anti-apoptosis, angiogenesis and invasion of prostate cancer cells." (PMID 23824300, 2013). "We show here that c-Myc, which is a key mediator of ligand-independent prostate cancer growth, is a key ligand-independent AR target gene." (PMID 23704919, 2013). "Neuropeptide bombesin can activate AR and confer androgen-independent growth of prostate cancer cells." (PMID 24349321, 2013). "Blockade of androgen receptor (AR) signaling represents the main treatment for advanced prostate cancer." (PMID 24086346, 2013).
prostate carcinoma (continued). "Transient transfection into prostate epithelial cells showed that human Zimp7 augments the transcriptional activity of the androgen receptor (AR), which is known to be of importance in the survival of prostate cancer cells." (PMID 24137407, 2013). "Previous studies have shown that the androgen receptor is essential for cell viability and proliferation of prostate cancer cells." (PMID 24062781, 2013). "Our results define a new link between two critical proteins in prostate cancer – AR and c-Myc – and demonstrate the potential of AR and c-Myc-directed therapies to improve prostate cancer control." (PMID 23704919, 2013). "These indicate that AR persistently stays at the center of therapeutic targets even after castration-resistant progression of prostate cancer." (PMID 23896594, 2013). "Vav3 enhances androgen receptor (AR) activity during progression to androgen independence in prostate cancer." (PMID 23566222, 2013). "The effects of androgen/AR signaling on senescence in prostate cancer cells remain a matter of controversy." (PMID 24244503, 2013). "Androgen receptor (AR) has been identified as a key driver of localised and metastatic prostate cancer and a principal therapeutic target." (PMID 23724116, 2013). "A recent study showed that MED1 plays an essential role in chromatin looping at the castration-resistant prostate cancer-specific AR target UBE2C gene locus." (PMID 23887938, 2013). "It is anticipated that these new classes of anti-AR drugs will provide an additional arsenal to treat castration-resistant prostate cancer." (PMID 23771019, 2013). "Our group has identified c-jun as an important key player in this interaction between AR and taxanes which affects the outcome of treatment in the castration resistant status of prostate cancer cells." (PMID 24260253, 2013). "As a consequence of overexpression, increased AR sensitizes prostate cancer cells to low levels of androgen, leading to castration-resistant progression." (PMID 23896594, 2013). "The critical role of HSP90 in the stabilization, maturation and activation of AR and other proteins that contribute to the progression of prostate cancer highlights the potential of HSP90 inhibitors as therapeutic agents." (PMID 23674566, 2013). "AR remains indispensable for the proliferation of prostate cancer cells that have become castrate-resistant; AR-specific shRNA or siRNA blocks proliferation of androgen-sensitive as well as castration-resistant AR-positive prostate cancer cells." (PMID 23437213, 2013). "The aberrant activity of stem cell pathways, and their regulation by the Androgen Receptor (AR), has the potential to provide insight into novel mechanisms and pathways to prevent and treat advanced, castrate-resistant prostate cancers." (PMID 23326489, 2013). "It has been shown that 14-3-3zeta is an androgen-responsive gene that activates proliferation, cell survival, and androgen receptor transcriptional activity and facilitate the progression of prostate cancer." (PMID 24103426, 2013). "Prior studies have shown an inverse relationship between CAG repeat length and AR transcriptional activation ability, and short CAG repeat lengths correlate with an increased risk of developing prostate cancer." (PMID 23359804, 2013). "These “clients” include AR and a range of oncoproteins involved in diverse cellular pathways, making it an attractive target for prostate cancer." (PMID 23674566, 2013). "Other studies have shown that estradiol (E2) can directly bind to AR of DU145 cell lines of prostate cancer cells and enhance the transcriptional activity of AR." (PMID 24282788, 2013). "Active research efforts have resulted in an enhanced understanding of the persistent role of androgen and AR in advanced prostate cancer." (PMID 24482578, 2013).
prostate carcinoma (continued). "Compounds found in W. chinensis have been recently reported to attenuate androgen receptor activity and orthotropic growth of prostate cancer in nude mice via the inhibition of androgen receptor signaling pathway." (PMID 23734189, 2013). "Several data favor androgen receptor implication in prostate cancer initiation through the induction of several gene activation programs." (PMID 23840433, 2013). "The AR is a ligand-dependent transcription factor, and the targeting of androgen- and AR-signaling axis remains the primary therapeutic option for Prostate cancer (PCa) treatment." (PMID 26877888, 2013). "Anti-Androgens are AR antagonists that are often used clinically in conjunction with ADT or as a monotherapy to block AR activity in prostate cancer cells." (PMID 23326489, 2013). "AR, the key transcription factor in prostate cancer regulates glycolytic metabolism and lipid, amino acid and nucleotide biosynthesis." (PMID 23724116, 2013). "Thomas and colleagues demonstrated that Stat5 (signal transducer and activator of transcription 5) stabilizes AR and potentiate castration-resistant progression of prostate cancer cells." (PMID 23896594, 2013). "Some androgen-independent sublines derived from originally androgen-dependent LNCaP prostate cancer cells overexpress the AR and PSA, for which silencing the AR gene suppresses cellular proliferation." (PMID 23896594, 2013). "We reported previously that Casodex (bicalutamide), a specific inhibitor of AR, blocks the ability of G1 phase AR-positive LNCaP prostate cancer cells to enter S phase, indicating a role of AR in cell cycle progression from G1 to S phase." (PMID 23437213, 2013). "A plausible candidate ARV chaperone is HSP27, which was found to bind directly to the AR NTD in vitro and has been linked to treatment resistance and cell survival in prostate cancer." (PMID 23674566, 2013). "This peptide derives from the AR sequence responsible for association of a proline rich sequence of AR with Src-SH3 domain and competes for this association in androgen-challenged prostate cancer LNCaP cells." (PMID 24130806, 2013). "PFKFB2 has been shown to be upregulated as a consequence of the transcriptional changes orchestrated by the androgen receptor in prostate cancer cells, with possible control through the AR-CAMKII-AMPK signaling pathway." (PMID 24280138, 2013). "Using a yeast two-hybrid screen and co-immunoprecipitation, we have identified a novel transcription complex AR-p44-Smad1 in prostate cancer cells." (PMID 23734213, 2013). "The recent FDA approval of enzalutamide (formerly MDV3100) confirms the continued critical role AR signaling plays in castration-resistant prostate cancer." (PMID 23580326, 2013). "Consistent with this, a siRNA phenotypic screen identified MAK3K11 as a kinase regulating prostate cancer cell growth through modulating the AR transcriptional program." (PMID 23896594, 2013). "It is well-appreciated that the AR is a critical driver of prostate cancer cell survival and that AR accounts for progression to fatal CRPC despite treatment with ADT." (PMID 23704919, 2013). "The presence of a primarily AR-independent subpopulation in prostate cancer cells has long been suggested as a potential mechanism for castration-resistant progression of prostate cancer." (PMID 23896594, 2013). "In our study, we found that RWPE-1 cells, an AR positive cell line, expressed MUC1, a phenomenon contrary to the proposed mode of action of AR in prostatic cancer cells." (PMID 23451223, 2013). "In mice, the introduction of constitutively active AKT kinase in Sca-1-enriched prostate epithelial cells resulted in tumor initiation and, in human cells, over-expression of AKT, ERG and AR in luminal cells generated prostate cancer." (PMID 24086346, 2013).
prostate carcinoma (continued). "The diverse network of interactions shown for SKIP, in particular with nuclear hormone receptors, explains its impact on several signalling pathways involved in growth and development, including possibly in AR-dependent prostate cancer cell growth." (PMID 23566155, 2013). "In vitro growth assays were conducted to examine the consequences of AR F876L expression on enzalutamide sensitivity in prostate cancer cell lines." (PMID 23580326, 2013). "Recent studies have suggested that EGFR or ERBB2 contribute to prostate cancer (PCa) progression by activating the androgen receptor (AR) under hormone-poor conditions." (PMID 24223781, 2013). "To further confirm that AR promotes expression of c-Myc in a ligand-independent manner, we treated prostate cancer cells with the new, potent androgen antagonist MDV3100." (PMID 23704919, 2013). "We first examined the mRNA expression of GNMT in the LNCaP, AR-positive prostate cancer cell line, which is dependent on androgens for growth." (PMID 23997240, 2013). "Prostate cancer is driven largely by male hormones, otherwise known as androgens, acting through the androgen receptor." (PMID 23580166, 2013). "Guo and colleagues reported that Src tyrosine kinase phosphorylated AR and conferred castration resistance to prostate cancer cells upon EGF stimulation." (PMID 23896594, 2013). "The effects of silencing androgen receptor (AR), beta-catenin and Akt expression in prostate cancer growth and migration were examined." (PMID 23455493, 2012). "Recent therapeutic advances for managing advanced prostate cancer include the successful targeting of the androgen-AR axis with several new drugs in castrate resistant prostate cancer including abiraterone acetate and enzalutamide (MDV3100)." (PMID 22956944, 2012). "The accepted androgen receptor (AR) role is to promote proliferation and survival of prostate epithelium and thus prostate cancer progression." (PMID 22403609, 2012). "The DU145 and PC-3 lines were derived from brain and bone metastases of prostate cancer, whereas the AR(+), PSMA(+) LNCaP cell line was derived from a lymph node metastasis." (PMID 23041906, 2012). "Genetic alterations in the promoter and 5'untranslated regions (UTR) of the AR gene have been also observed in prostate cancer cell lines, xenografts and in two prostate cancer patients." (PMID 22471922, 2012). "Our previous studies have shown that B-DIM is able to inhibit AR expression in prostate cancer cells." (PMID 23056607, 2012). "At least three mechanisms contribute to the reactivation of the androgen receptor in prostate cancer progression." (PMID 22548055, 2012). "Castration-induced normal prostate shrinkage (the standard treatment for prostate cancer) is in part dependent on actions in AR expressing cells in the prostate stroma." (PMID 24213323, 2012). "Our characterization of the interaction between Brd2 and H2A.Z nucleosomes also furthered our understanding of the role H2A.Z plays in promoting AR-regulated transcription in prostate cancer cells, yielding potential new molecular targets for therapy." (PMID 23144632, 2012). "Levels of INPP4B are found to be induced by the androgen receptor in prostate cancer cells and play an important role in androgen-ablation therapy of prostate cancers." (PMID 22121480, 2012). "LnCaP cells have been shown to retain androgen dependence and maintain the presence of androgen receptor (AR), thus resembling early-stage prostate cancer." (PMID 24624160, 2012). "Because previous studies showed ligand-independent activation of AR transcription by EGF in prostate cancer cells, we first assessed the effects of EGF and a specific EGFR inhibitor PD168393 on AR transactivation in bladder cancer lines." (PMID 22922989, 2012). "Previous studies have demonstrated that the activation of androgen receptors (AR) by androgens is required for the growth and survival of prostate cancer cells." (PMID 22363680, 2012).